KL (klotho)
Diseases named in the same sentence as KL in open-access papers (continued):
Sharing a sentence is not in itself a finding about the gene and the disease.
diabetes (continued). "Consequently, klotho may have the immunotherapeutic potential for the treatment of diabetes and its associated nephropathy by controlling levels of inflammation and oxidative stress." (PMID 37143722, 2023). "In the development of diabetes and diabetic nephropathy, various cell stress factors may directly cause cellular senescence or down-regulate anti-aging proteins (e.g., Sirt1 and Klotho) and indirectly cause cellular senescence; however, the specific mechanism remains to be elucidated." (PMID 36359836, 2022). "In summary, our studies provide evidence that in children with T1D, changes in miR-192 and KL correlate with risk factors for complications such as DN, and that changes in KL and/or miR-192 levels could serve as early biomarkers for diabetes complications in youth with T1D." (PMID 35992154, 2022). "Therefore, we came to a conclusion that Klotho deficiency may promote diabetes-induced podocytic MtD and aggravate 8-OHdG-induced DNA damage by affecting OOG1." (PMID 33162804, 2020). "Finally, another interesting observation was the significantly higher incidence of diabetes mellitus in subjects with the allele A variant, a difference that could be related to the lower levels of Klotho expression." (PMID 26538295, 2016). "Reduced Klotho levels may therefore increase cardiovascular risk in diabetes." (PMID 23945089, 2013). "Klotho, which mitigates diabetes-induced elevation of serum creatine kinase-muscle/brain (CK-MB) and LDH, cardiac fibrosis, cardiomyocyte apoptosis, and cardiac dysfunction, also inhibits NLRP3 activation and TNF-α, IL-1β, and IL-18 expression." (PMID 41399377, 2026). "Interaction analyses further indicated that age (p-interaction = 0.002), alcohol intake (p-interaction = 0.04), and diabetes status (p-interaction = 0.03) significantly modified the Klotho-BAA relationship." (PMID 41770768, 2026). "In contrast, baicalin, a flavone glycoside, was reported to restore KL expression and reduce oxidative stress under diabetes-induced kidney injury in a rat model." (PMID 41463028, 2025). "(2020) detected serum Klotho levels in patients with different stages of diabetes in a clinical study." (PMID 41438297, 2025). "In recent research, Klotho inhibits oxidative stress and activates the TRPC6 signaling pathway, protecting podocytes against apoptosis caused by HG levels/diabetes in vitro and diabetic mouse models." (PMID 40119098, 2025). "Study finds that reduced endogenous and exogenous Klotho synthesis and activity in diabetes circumstances trigger cascading pathways, including ERK1/2, p-38, and cell cycle arrest via PPAR-γ, which ultimately results in diabetic kidney disease." (PMID 40119098, 2025). "After adjusting for age, sex, race/ethnicity, CVD, vitamin D, CKD, hypertension, diabetes, calcium, and phosphorus, a one‐unit increase in WWI was associated with a decrease of 24.75 pg/mL in serum Klotho (Model 3: β = −24.75, 95% CI: −24.84, −24.66)." (PMID 40678338, 2025). "Preclinical Klotho therapy has been shown to ameliorate cardiovascular disease as well as diabetes‐related conditions." (PMID 40678338, 2025). "Klotho, a measure of lifespan, decreases with age, diabetes, kidney failure, neurological diseases (AD, Parkinson's disease (PD), stroke, amyotrophic lateral sclerosis, epilepsy, glioblastoma multiforme)." (PMID 40119098, 2025). "Renin angiotensin aldosterone system (RAAS) activation is observed in the context of diabetes and can induce kidney damage via oxidative stress or by downregulating anti‐ageing proteins such as Sirtuins and Klotho." (PMID 39497615, 2025). "On the whole, the research of Klotho in diabetes and its complications is showing a trend of gradual transformation from basic mechanism to clinical application, but there are still multiple challenges in this process." (PMID 41438297, 2025). "A schematic model was developed to elucidate the complex relationship between serum Klotho (sKlotho) levels, diabetes onset, and metabolic regulation." (PMID 41438297, 2025).
diabetes (continued). "For example, insulin resistance and diabetes can disrupt the normal function of Klotho, leading to reduced expression in the body." (PMID 40060377, 2025). "The overall evidence of clinical and epidemiological studies shows that Klotho is closely related to diabetes and its complications, but there are some differences between different research results." (PMID 41438297, 2025). "In the first study on plasma Klotho in CVD, typical cardiovascular risk variables were observed, including age, gender, cholesterol, blood pressure, and diabetes." (PMID 40119098, 2025). "This article will systematically summarize the research progress of Klotho in diabetes and its complications in recent years, focusing on its molecular mechanism, clinical application potential and future development direction." (PMID 41438297, 2025). "Our results show that in the subgroup analysis, ABSI is significantly correlated with Klotho protein in variables such as age, gender, smoking history, drinking history, and diabetes history." (PMID 40007807, 2025). "It has been reported that streptozotocin (STZ)-induced diabetes in rats lowers the kidney Klotho levels, which is related to kidney damage." (PMID 40119098, 2025). "In summary, Klotho from basic research to clinical transformation, is becoming a research hotspot in the field of diabetes." (PMID 41438297, 2025). "Another investigated the role of Klotho in the development of cardiac fibrosis in a long-term rat model resembling type 1 diabetes mellitus and found that serum levels of Klotho were reduced in diabetic rats, possibly promoting the fibrotic process." (PMID 38672115, 2024). "Klotho expression is significantly affected by a variety of conditions such as stress, hypertension, oxidative stress, diabetes, and various inflammatory disorders." (PMID 40799848, 2024). "Several previous studies have demonstrated a close association between downregulation of Klotho expression and diseases such as COPD, cardiovascular diseases, diabetes, and kidney diseases." (PMID 38287280, 2024). "Our research findings also indicate significant differences in creatinine levels and the occurrence of diseases such as myocardial infarction, heart failure, and diabetes among individuals with different Klotho levels." (PMID 38287280, 2024). "A recent study demonstrated that Klotho expression was significantly decreased in smooth muscle cells in patients with diabetes and atherosclerosis." (PMID 40799848, 2024). "Previous studies on diabetes have shown similar results, indicating a positive correlation between the levels of klotho and cognition in patients with diabetes." (PMID 39563739, 2024). "These variables included diabetes, coronary heart disease, age, serum phosphorus, serum calcium, iPTH, serum IS, and Klotho." (PMID 38385060, 2024). "Consistently, ApoE-knockout mice with streptozotocin-induced diabetes on a high-fat diet exhibited lower Klotho expression in vascular smooth muscle cells, along with increased expression of TGF-β and MMP9 and enhanced phosphorylation of ERK and Akt." (PMID 40799848, 2024). "Klotho plays a crucial role in regulating oxidative stress and preventing age-related diseases such as diabetes, neurodegenerative disorders, and CVD." (PMID 40799848, 2024). "P values for interactions for diabetes and sex among participants with serum Klotho ≥ 870.7 pg/ml; and for diabetes among participants with serum Klotho < 870.7 pg/ml, were lower than 0.05." (PMID 38017397, 2023). "Opposite to the results of the present work, a previous study using a similar rat model but only during 14 days of diabetes, found higher serum sKlotho and lower urine sKlotho and renal Klotho expression." (PMID 36982322, 2023). "In db/db mice, a model of type 2 diabetes mellitus, intraperitoneal injections of recombinant Klotho reduced proximal tubular damage, the number of apoptotic tubular cells, and kidney ROS levels." (PMID 36829798, 2023).
diabetes (continued). "Conversely, increasing klotho levels helped to delay the progression of diabetes and postpone the onset of diabetic complications." (PMID 37143722, 2023). "Klotho levels show a decreasing trend in both type 1 diabetes mellitus (T1DM) and T2DM, and it is even depleted in the pancreas of diabetic patients." (PMID 37143722, 2023). "Circulating Klotho levels are significantly reduced in subjects with type 2 diabetes mellitus (T2DM) and in kidney disease patients." (PMID 37686263, 2023). "Klotho protects cells against accelerated aging and damage during the course of diabetes and diabetic nephropathy by several mechanisms, including the inhibition of inflammation." (PMID 37686263, 2023). "In conclusion, in our study, it is suggested that high levels of Klotho have a protective effect against anemia in middle age and that this effect is more pronounced in men and in diabetes." (PMID 36797683, 2023). "Serum miRNA-192 concentrations were negatively associated with circulating KL levels in children with prolonged duration of diabetes, suggesting a potential regulatory role for miRNA-192 in soluble KL expression." (PMID 36835983, 2023). "The table shows 14 study variables, which are composed of Serum Klotho, ApoB, Gender, Age, Race, Education level, Ratio of family income to poverty, Hypertension, High cholesterol level, BMI, Diabetes, Drinking, Smoking, and Cancer." (PMID 37352065, 2023). "More specifically, klotho regulates the upregulation of autophagic flux by inhibiting the AKT/mTOR pathway or the IGF-1-mediated PI3K/Akt/mTOR pathway to improve diabetes and kidney injury." (PMID 37143722, 2023). "Renal atrophy (typically nephrosclerosis) can be severe in patients with diabetes or hypertension, and because most circulating Klotho originates from the kidney this can lower levels." (PMID 35903083, 2022). "Our results show that circulating KL levels are negatively correlated to HbA1c and diabetes duration after adjusting for age." (PMID 35992154, 2022). "There are no studies reporting the role of SGLT-2 inhibitors in people with diabetes on Klotho, an emerging biomarker of arterial aging and cardio-renal risk." (PMID 36247425, 2022). "In all three regression models (Model 1-3), the increase in serum Klotho levels was positively correlated with the prevalence of diabetes." (PMID 36440221, 2022). "In the kidney, which is the main site of production, various factors can alter Klotho expression under physiological and pathological conditions, such as circulatory stress, hypertension, oxidative stress and diabetes." (PMID 35903083, 2022). "Patients with type 1 diabetes mellitus show decreased klotho levels compared to the normal population." (PMID 36140700, 2022). "In recent years, the role of Klotho in diabetes and kidney disease has attracted increasing attention." (PMID 35692408, 2022). "Participants with the lowest Klotho concentration were more likely to have diabetes and CVD and use hypotensive, hypoglycemic, and lipid-lowering medications." (PMID 36457804, 2022). "Our in vitro experiments provide proof of concept for a role of miR-192 in influencing KL levels, as well as pathophysiological processes such as oxidative stress, inflammation or senescence that play a role in diabetes complications." (PMID 35992154, 2022). "Numerous studies involving both genetic and experimentally-induced animal models of diabetes suggest the significant cardio-renal benefits of Klotho." (PMID 36440221, 2022). "The overall prevalence of diabetes was 25.9% (n = 3557), which was 27.1% (n = 933), 24.5% (n = 842), 24.7% (n = 850) and 27.1% (n = 932) in serum Klotho quartiles 1-4, respectively (P = 0.01)." (PMID 36440221, 2022). "β cell-specific expression of Klotho preserved the β cell function, ameliorated hyperglycemia, enhanced glucose tolerance and prevented the development of diabetes in db/db mice." (PMID 36440221, 2022).
diabetes (continued). "This study aimed to investigate the relationship between serum Klotho levels and diabetes in US adults." (PMID 36440221, 2022). "We found that renal cortical Klotho expression is significantly downregulated in diabetes and its expression was restored by the deletion of C5aR1." (PMID 36434087, 2022). "Additional studies elucidating the mechanisms linking glycemic control and s-Klotho levels and exploring their predictive ability of clinically meaningful outcomes in patients with diabetes are needed." (PMID 35286490, 2022). "In contrast, some researchers have reported that serum Klotho levels are greatly upregulated in patients with diabetes compared with the levels in healthy controls." (PMID 36440221, 2022). "Collectively, these findings support the crucial role of Klotho in preventing the development of cardio-renal dysfunction induced by diabetes." (PMID 36440221, 2022). "As compared with quartile 1, serum Klotho levels in quartiles 2-4 yielded odds ratios (OR) (95% CI) of diabetes of 0.96 (0.80–1.15), 0.98 (0.82–1.18), and 1.25 (1.04–1.50), respectively, after covariate adjustment (P for trend = 0.018)." (PMID 36440221, 2022). "Klotho is also considered an antiaging factor that induces IR and participates in the pathogenesis of diabetes." (PMID 36325267, 2022). "In accord, preclinical Klotho therapy ameliorated renal, cardiovascular, diabetes-related and neurodegenerative diseases, as well as cancer." (PMID 35903083, 2022). "Early vascular aging and endothelial dysfunction are hallmarks of cardio-renal disease in diabetes, and are highly related to upregulated renal expression and decreased serum and urine Klotho levels." (PMID 36440221, 2022). "In the case of diabetes treatment, a caveat is that metformin increases insulin sensitivity whereas Klotho has the opposite effect." (PMID 35903083, 2022). "Soluble Klotho improves hepatic glucolipid homeostasis to ameliorate diabetic phenotypes and lipid accumulation in the mice model with type 2 diabetes mellitus in comparing wild-type, soluble Klotho heterozygous, and soluble Klotho transgenic group." (PMID 35053218, 2022). "Taken together, the discrepancies among previous publications can be largely attributed to the dynamic changes in Klotho expression at different stages of diabetes." (PMID 36440221, 2022). "Most of the published evidence is from adults with diabetes and kidney disease, while studies examining circulating KL levels in children with type 1 diabetes (T1D) are very limited." (PMID 35992154, 2022). "It is noteworthy that previous evidence concerning the changes in serum Klotho levels in the context of diabetes is contradictory." (PMID 36440221, 2022). "Likewise, reduced serum Klotho levels were strongly linked to a faster rate of decline in estimated glomerular filtration rate (eGFR) in diabetic patients, implying that reduced Klotho levels may predict diabetes-associated renal impairment." (PMID 36440221, 2022). "Recombinant Klotho protein therapy has been successfully applied to the treatment of renal, cardiovascular and neurodegenerative disease, as well as diabetes and cancer." (PMID 35903083, 2022). "Downregulated Klotho expression was consistently observed in pancreatic islet β cells of diabetic human patients and in a rodent model of diabetes (db/db mice)." (PMID 36440221, 2022). "Does Klotho contribute to the therapeutic effects of some drugs used to treat hypertension, hyperlipidemia, diabetes or transplant rejection?" (PMID 35903083, 2022). "Future longitudinal investigations are required to determine the predictive value of Klotho in the context of diabetes." (PMID 36440221, 2022). "Intracerebroventricular injection of Klotho in diabetes-prone mice reduced food intake, ameliorated glucose homeostasis and reduced body weight." (PMID 35903083, 2022). "Production and function of klotho are reduced in obese diabetes, and rKL administration can make up for those losses." (PMID 33891667, 2021).
diabetes (continued). "Klotho induces insulin production and secretion in vitro and in vivo, attenuates insulin sensitivity in mice, and is depleted in pancreatic islets of type 2 diabetes mellitus (T2DM) patients." (PMID 34944918, 2021). "Moreover, diabetes-induced proteinuria, oxidative stress (reflected by intracellular ROS levels), podocyte injury, and apoptosis that was caused by protein kinase Cα (PKCα) activation were aggravated by Klotho deficiency and partially ameliorated by Klotho overexpression." (PMID 33478014, 2021). "Restoring full-length Klotho expression in db/db mice attenuated the development of diabetes, enhanced glucose tolerance, and restored LC3 expression in islet β-cells." (PMID 34737707, 2021). "Twenty-four hour urinary microalbumin increased significantly by more than 10 times after diabetes and decreased to some extent after overexpression of Klotho." (PMID 32054986, 2020). "Our results further confirmed the protective roles of Klotho on diabetes-induced DNA damage of podocyte, how Klotho regulates OGG1 inhibiting 8-OHdG remains to be further studied." (PMID 33162804, 2020). "Further analysis by immunofluorescence suggested 8-hydroxydeoxyguanosine (8-OHdG), a marker of DNA damage, increased with diabetes, especially in KL+/- STZ, which was inversely related to the expression of Nephrin." (PMID 33162804, 2020). "The correlation of research between Klotho and ROS in diabetes is mainly in ROS-induced podocyte apoptosis." (PMID 33162804, 2020). "Aging is associated with a reduction in the renal expression and serum concentrations of Klotho, which is also observed in diseases characterized by premature vascular aging, such as renal failure, hypertension, and diabetes mellitus." (PMID 31986490, 2020). "As high embryonic mortality and failure rate of diabetes model in Klotho homozygous mice, we selected Klotho heterozygous mice." (PMID 33162804, 2020). "We found that the level of serum klotho was negatively related with diabetes mellitus after adjusted for age." (PMID 30791885, 2019). "Consecutively, MCS-D-EPCs showed increased Sod-2 expression, indicating that the presence of Klotho in MCS induces Sod-2 expression in D-EPCs leading to resistance to diabetes-induced oxidative damage." (PMID 30153276, 2018). "Blood glucose and insulin levels decreased in Klotho gene knockout mice, although insulin sensitivity increased, suggesting that Klotho is closely related to the incidence of diabetes." (PMID 29900135, 2018). "In fact, the latest studies exploring Klotho upregulation in animal models of diabetes and diabetic nephropathy have shown promising results in protecting pancreatic islet cells and reducing renal fibrosis." (PMID 27668003, 2016). "Depleted protein expression of Klotho has been described in pancreatic islets in animal models of diabetes, and moreover, in vivo expression of Klotho in pancreatic β cell preserved its functionality and attenuated the development of diabetes in db/db mice." (PMID 26538295, 2016). "Despite these observations, the role of klotho in diabetes-induced renal hypertrophy and fibrosis and the precise molecular mechanism remain to be elucidated." (PMID 25695625, 2015). "In contrast, the serum levels of soluble Klotho were decreased in patients with early stages of CKD in a different study including 15.4% diabetes mellitus cases." (PMID 23431388, 2013). "Studies have found that the relationship between the TyG index and Klotho levels varies depending on the presence of diabetes, indicating a complex interaction that may contribute to differential aging outcomes in various metabolic states." (PMID 40376115, 2025). "Mechanism and clinical value of Klotho in complications of diabetes." (PMID 41438297, 2025). "Furthermore, a significant inverse relationship between WWI and serum Klotho was found when stratified by age, diabetes status, BMI, and hypertension." (PMID 40678338, 2025).